SP1 (Sp1 transcription factor)
Diseases named in the same sentence as SP1 in open-access papers (continued):
Sharing a sentence is not in itself a finding about the gene and the disease.
cancer (continued). "The binding of Sp1 to G-C-rich promoters was inhibited by RSV, resulting in the reduced expression of cancer-related genes (p27, p21, cyclin D1, and Mcl-1) under the control of Sp1." (PMID 32933137, 2020). "It is known that the transcription factor Sp1 upregulates SK1 under certain conditions, which is important in neuronal growth and possibly cancer." (PMID 33171624, 2020). "We chose to study SP1 through preliminary validation in CRC tissues via qRT-PCR, which is dysregulated in different cancers." (PMID 32231999, 2020). "In contrast, NWXF treatment inhibited the binding activity of Sp1 to the MMP2 promoter, resulting in decreased MMP2 expression, which is crucial for cancer migration and invasion." (PMID 33329003, 2020). "This is further substantiated by the fact that normal cells have lower levels of Sp1 and c-MYC than cancer cells." (PMID 33329574, 2020). "Typically, TERT interacts with TF Sp1, binding to the vascular endothelial growth factor (VEGF) promoter and facilitating VEGF transcription/cancer angiogenesis in human cancer cells and xenograph mouse cancer models." (PMID 31284662, 2019). "In H-score analysis, we found significantly increased expression levels of Sp1, PKCι, and TMBIM6 proteins in cancer tissues from normal tissues." (PMID 31336725, 2019). "Altogether, this study suggests the involvement of Sp1 in basal transcription and PKC in the enhanced expression of TMBIM6 in cancer." (PMID 31336725, 2019). "Overall, these results suggested that SP1 activated ABCC1 and stimulated the expression of the CCNE1, ERF, and MYB genes, which have been shown to be related to chemoresistance and cancer relapse." (PMID 31118037, 2019). "The reduced p16INK4a nuclear localization by overexpression of hYSK1 leads to the activation of SP-1 transcriptional activity, resulting in increased MMP-2 expression and enhanced cancer cell proliferation and migration." (PMID 30646538, 2019). "Specificity protein 1 (Sp1), a zinc-finger transcription factor, directly regulates RIPK3 expression in cancer cells." (PMID 31719524, 2019). "Target genes of miR-22 so far reported include HDAC4, CDK6, SIRT1, SP1, HIF-1α and PTEN, which are involved in cancer progression." (PMID 30379969, 2018). "Based on the results, we found that STAT6, a cancer-related TF, regulated FOS and FOSB, while FOS and EGR1 were coregulated by 2 cancer-related TFs, including BRCA1 and SP1, respectively." (PMID 30228980, 2018). "Our study suggests that cancer cells accelerate the aggressiveness of a malignancy by themselves via cooperation between ZEB2 and Sp1 and subsequent acquirement of a proliferative and viable phenotype." (PMID 29416649, 2018). "Our previously published data shows that GRP78‐mediated ER homeostasis is dependent on SP1 activity and inhibition of SP1 prevents the homeostasis and pushes the UPR to a chronic ER stress phase, leading to cancer cell death." (PMID 29738634, 2018). "KEGG pathway analysis indicated these 47 mRNAs were involved into the pathways in cancer, especially ROCK, STAT3 and SP1." (PMID 30474931, 2018). "The PHGDH promoter is positively regulated by specificity protein 1 (SP1) and nuclear transcription factor Y (NFY), two transcription factors that are often upregulated in cancer." (PMID 29740540, 2018). "In conclusion, we demonstrate that, besides its role in cancer cell invasion, ZEB2 directly promotes CTC survival and tumor angiogenesis through cooperation with Sp1." (PMID 29416649, 2018). "By transcription factor enrichments analysis, many cancer-related genes from the overlap of DEN and DEN+DR signature genes were enriched in SP1 network." (PMID 28262799, 2017). "The SP1 gene is itself among the FOXO4 targets and was found to be up-regulated in cancer cell lines." (PMID 28798381, 2017). "Hallmark capabilities enabled by epithelial-mesenchymal transition include sustained proliferation, with cell cycle components controlled by SP1, LEF1, and FOXO4 up-regulated in cancer cell lines." (PMID 28798381, 2017).
cancer (continued). "AGEs-RAGE signaling cascade induced the cancer cell invasion and migration partially through increasing expressions of RAGE, Sp1, and MMP2." (PMID 29262634, 2017). "From HTR-8/SVneo and JEG-3 cells tested, we showed that SP1 facilitated the expression of DNMT1, which is consistent with previous reports in various human cancers and mouse NIH3T3 cells." (PMID 29163762, 2017). "Specificity protein 1 (SP1) and Forkhead Box M1 (FOXM1) also potentiate UHRF1 expression in different cancers." (PMID 28881702, 2017). "Here, we report that Sp1, a well-characterized zinc-finger transcription factor, directly regulates RIP3 expression in cancer cells." (PMID 28981102, 2017). "FHL1 expression, induced by ionizing irradiation in a SP1- and MLL1-dependent manner, positively correlates with radioresistance in cancer patients." (PMID 28094252, 2017). "Taken together, these observations indicated that PI3K/AKT pathway is responsible for TGF‐β‐mediated SP1 stabilization and further confirmed that SP1 is crucial for TGF‐β‐mediated up‐regulation of NKG2DLs in cancer cells." (PMID 28165192, 2017). "For instance, motifs of the TFs SP1, MAZ, and the CAC-binding protein were shared by GSs from at least three of the five cancer types." (PMID 28684851, 2017). "Previous studies have demonstrated that transcription factors including Sp-1, AP-1, and NF-κB play​​ a key role in the regulation of MMP-9 in cancers." (PMID 28680385, 2017). "Since both Sp1 and PLD1 contribute to the aggressive of various human cancers, we postulated that they were correlated in the disease." (PMID 27713167, 2016). "Both Cur and TA have shown anti-cancer activity in multiple cancers including CRC by targeting NF-κB and Sp1 respectively." (PMID 26672603, 2016). "Sequence-specific transcription factors, such as early growth response protein 1 (Egr1) and SP1, can increase VEGF transcription in cancer cells." (PMID 26848522, 2016). "We also detected for the first time in RAJI cells the presence of a GGGGC(2×) repeat insertion in the Sp1 region of AHR promoter (SNP rs71010234), a SNP previously reported for other cancer cell lines and human samples." (PMID 27006469, 2016). "Overexpression of SP1 has been shown to overcome the inhibitory effect of curcumin on EP4 promoter activity and protein expression in other cancer cell types." (PMID 26689593, 2015). "As it has been reported for other anti-cancer proteins such as SP1, UBXN2A's up- and down-regulation can coordinate with the stage of cancers." (PMID 26188124, 2015). "Two related transcription factors with known roles in cancer, Sp1 and KLF4, bind to the SLC4A7 promoter, exerting opposite functions: Sp1 represses and KLF4 activates SLC4A7 transcription." (PMID 24795638, 2014). "In the present study, we found that Sp1, which accumulated in the early stages of cancer, positively regulated miR-182 gene expression to silence FOXO3 expression and thereby promote cancer cell growth." (PMID 24519909, 2014). "Cancer cells use CDK1 and PP2A to regulate the movement of Sp1 in and out of the chromosomes during the cell cycle." (PMID 25398907, 2014). "Previous studies have indicated that the AKT/SP-1 pathway regulated MMP-2 promoter activity and affected the migration ability of cancer cells." (PMID 23799155, 2013). "Regarding tumor metabolism under hypoxic conditions, it has recently been found that Sp1 cooperates with HIF-1 to promote glycolysis in solid tumors and thus, facilitating cancer metabolic reprogramming and tumor progression." (PMID 23326553, 2013).
cancer (continued). "Further, it has been reported that knockdown or downregulation of Sp1, Sp3, and Sp4 represses expression of Sp-regulated genes, including VEGF and BCL-2, inhibits cancer cell growth, and induces apoptosis." (PMID 23626851, 2013). "The activation of the SP-1 downstream of the MAPK or PI3K-Akt pathways is involved in numerous pathological processes, such as inflammation, cancer-cell adhesion, tumor invasion, metastasis, and angiogenesis." (PMID 23437203, 2013). "It changes a putative stimulatory protein (Sp1) binding site in the promoter of COX-2 between-766 and-761 bp, but it creates an E2 promoter factor (E2F) binding site, leading to high transcription activity, which may be the mechanism of COX-2-765G>C polymorphism increasing cancer risk." (PMID 24023834, 2013). "Overall, our results reveal a novel cooperative role of Brg-1 and Sp1 in mediating the constitutive and fenretinide-induced expression of SPARC, and provide new insights for the understanding of the anti-cancer effects of fenretinide." (PMID 20687958, 2010). "Other studies in cancer cell lines showed that several NR4A1-regulated integrins, including β1-, β4-, α5- and α6-integrins, were coregulated by NR4A1 interactions with Sp1, Sp3 and Sp4; however, the role of individual Sp TFs was gene and cell context-dependent." (PMID 39858066, 2025). "Towards this, we processed SP1 ChIP-seq from a metastatic (Colon: HCT116) and a non-metastatic (Breast: MCF7) cancer cell line from the ENCODE database and further analysed to identify SP1-drive transcriptional circuitry in these cell models." (PMID 39748426, 2025). "Since the functional differences between sp1 and sp2 isoforms are still unknown, they may be crucial for a unique function of EMX2 in cancer cells." (PMID 40564092, 2025). "By emphasizing SP1’s pivotal role in the FGR-DKK1 axis and detailing its regulation through PI3K-AKT signaling, our research enhances the understanding of the elaborate signaling networks that govern gene expression in cancer." (PMID 39788945, 2025). "Peroxisome proliferator-activated receptor (PPAR): PPARƔ interacts with Sp1 (and Sp3) to regulate gene expression in both cancer and non-cancer cells, and most of these responses include interactions with other nuclear factors." (PMID 39858066, 2025). "SP1 features conserved zinc finger motifs in its DNA-binding domains, which recognize GC-rich (SPs) and CACC (KLFs) boxes, which allows SP1 to regulate various cellular processes, including cell proliferation, cancer metastasis, and cancer stemness." (PMID 39757165, 2025). "COUP-TF interacts directly with Sp1 and COUP-TF/Sp1 alone and, in combination with other nuclear factors, regulates the expression of NGF1-A and human immunodeficiency virus type 1 (HIV-1) in non-cancer cells." (PMID 39858066, 2025). "The finding that FGR’s influence on DKK1 is mediated through a signaling pathway involving SP1 highlights the intricate regulatory processes that dictate cancer cell behavior and identifies the FGR-PI3K-AKT-SP1 pathway as a valuable target for therapeutic intervention." (PMID 39788945, 2025). "Furthermore, knockdown of SP1 in S2-013 and HPAF-II cells by siRNA abrogated the acetate-induced increased survival of cancer cells in low-pH conditions." (PMID 38429478, 2024). "Researchers have explored the relationship between Sp1 and cancer, defining the Sp transcription factor as the non-oncogene addiction gene." (PMID 39228402, 2024). "Therefore, the data overall indicated that M4N was a dual inhibitor for SP1 and HIF1A and occasionally worked as an inhibitor for MYC in certain cancers." (PMID 39590335, 2024). "In addition, it was shown by promoter analysis that the expression of many cancer stem cell (CSC)-related genes such as TERT, BMI1, BSG (CD147), and PROM1 (CD133) was under the control of SP1, HIF1A, and MYC." (PMID 39590335, 2024).
cancer (continued). "Likewise, mir-186 suppressed SP1, MYC, and HIF1A, and the induction of mir-186 induces the sensitivity of cancer cells to anticancer drug." (PMID 39590335, 2024). "Although the treatment of cancer cells with acetate led to an induction of wild-type SP1 protein expression, K19R mutant SP1 failed to stabilize in the presence of acetate." (PMID 38429478, 2024). "The fact that the genes involved in the regulation of CSCs are all controlled by SP1, HIF-1, and MYC indicates that the very reason why these TFs are important participants of cancer regulatory networks might be because they regulate CSCs." (PMID 37998757, 2023). "Although many inhibitors of either HIF-1 or SP1 have some anticancer activity, none of them have activity strong enough to eradicate cancer in the majority of patients." (PMID 37998757, 2023). "Interestingly, in all of these studies, three TFs, namely SP1, HIF1A, and MYC, were among the factors that participated in the cancer regulatory network." (PMID 37998757, 2023). "Functional studies have demonstrated that the SP-like family of TFs regulates various genes responsible for cancer-related cellular mechanisms; SP1, SP3, and SP4 are also non-oncogene addiction (NOA) genes and thus are important drug targets." (PMID 37998757, 2023). "Together, these data suggest that SP1, HIF1A, and MYC have crucial roles in cancer development, and that interfering with their activity could negatively impact cancer development and progressions." (PMID 37998757, 2023). "Sp1 is a known target in some forms of cancer, but the effects of such inhibition on TAMs have not yet been explored." (PMID 36979068, 2023). "We recently identified that transcription factor SP1 is an inhibitor for USP22 gene expression, and here we found that FT671 treatment induced a significant decrease of SP1 protein in both A549 and H1299 cancer cells." (PMID 37946202, 2023). "Furthermore, we performed immunohistochemistry to detect the expression of SP1 in LUAD tissues and para-carcinoma tissues." (PMID 36964266, 2023). "Interestingly, quantities of Sp1, Sp3 and Sp4 were found to be suppressed in ZBTB4-overexpressing cancer cells." (PMID 36615262, 2022). "Similar results were also observed in AGO1, RPS27A, SP1, and ETS2 of several cancers." (PMID 35911954, 2022). "Moreover, betulinic acid exerted repressive effects on the levels of Sp1, Sp3 and Sp4 in tumor tissues of mice xenografted with BT474 cancer cells." (PMID 36615262, 2022). "Furthermore, we uncover that TBX2/CoREST targeting of NDRG1 is achieved by recruitment of TBX2 to the NDRG1 promoter by Sp1, the abolishment of which resulted in NDRG1 upregulation and diminished cancer cell proliferation." (PMID 35687133, 2022). "As PFKP Y64 phosphorylation regulates PI3K/AKT in EGFR-activated cancer cells, we investigated whether PFKP Y64 phosphorylation could modulate SP1 activity." (PMID 36435833, 2022). "There is evidence that upregulated SP-1 plays a crucial role in cell proliferation and metastasis of various tumors; thus, it is considered to be a negative factor in cancer prognosis." (PMID 34876130, 2021). "It has been reported that Sp1 is closely related to cancers, and high level of Sp1 in human blood is perceived as a negative prognostic factor to cancers." (PMID 34124031, 2021). "Indeed, analyses from the UALCAN database revealed that the expressions of SP1, ELK1, and EGR1 were remarkably aberrant in many TCGA cancer types." (PMID 35003212, 2021). "In addition, it has been shown that Sp1 and STAT3 are transcription factors that regulate VEGF expression and VEGF secretion of cancer cells." (PMID 34458134, 2021). "Concerning transcription factors, sets of the most important features are less similar to each other for different cancer types but nevertheless CTCF, GABPA, RXRA, SP1, MAX and NR2F2 are more frequently included in top features than other transcription factors." (PMID 33647036, 2021).
cancer (continued). "Our data revealed Sp1 as a key factor in a previously unexplored metastatic cascade in CSCC and promote further screening and potential development of Sp1-specific inhibitors in cancer therapy." (PMID 33484377, 2021). "According to the prediction results of starBase20, 229 miRNAs binding to SP1 (screening conditions: CLIP-Data ≥ 1, Degradome-Data ≥ 0, and pan-Cancer ≥ 4) and 107 miRNAs interacting with circ_0026628 (screening conditions: CLIP-Data ≥ 1 and Degradome-Data > 0) were discovered." (PMID 34420031, 2021). "SP1 is one of the transcription factors and belongs to the Sp/Krüppel like factor (KLF) family that plays multiple roles in maintaining cellular homeostasis and critical factors in diseases including cancer." (PMID 32726929, 2020). "On the basis of these findings, we concluded that high levels of Sp1 in malignant/stemlike GBM cells modulated the balance between prosurvival and prodeath signals, thereby protecting these cells against stress conditions and cancer therapies." (PMID 32326583, 2020). "On the basis of current and previous findings, high levels of Sp1 in malignant/stemlike GBM cells modulated the balance between prosurvival and prodeath signals, thereby protecting GBM cells from stress conditions and cancer therapies." (PMID 32326583, 2020). "While activation of Sp1 is known to regulate the expression of genes related to cancer progression, the role of Sp1 in lysosomal activation has not yet been reported." (PMID 33110168, 2020). "Interestingly, overexpression of PADI driven by MZF1 and Sp1/Sp3 binding to the promoter region can citrullinate PKM2 and stimulate glycolysis in cancer cells." (PMID 32002016, 2020). "This may be explained by a cancer cell-type specific role of YY1, HSF1 and SP1 in regulating basal Ub gene expression." (PMID 32751694, 2020). "The influence of SP1 and SP3 expression on CGB expression in cancer is very difficult to assess." (PMID 31362717, 2019). "Additionally, celecoxib reduces the transcriptional activity of Sp1, which down-regulates VEGF expression by cancer cells." (PMID 30974834, 2019). "Indeed, dysregulation of either Sp1, p11, or TASK1 has been independently reported in multiple pathological conditions, including inflammatory processes and cancer, affecting different organs and tissues." (PMID 31439839, 2019). "Indeed, TERT synergized with Sp1 to stimulate the DNMT3B promoter activity, and moreover, Sp1 inhibition significantly attenuated TERT-mediated DNMT3B up-regulation, while its over-expression restored DNMT3B expression in TERT-depleted cancer cells." (PMID 31284662, 2019). "Furthermore, this study explored the significance of the Sp1 and PKC in the upregulation of TMBIM6 expression in cancers." (PMID 31336725, 2019). "The Specificity Protein 1 (SP1) transcription factor has been shown to contribute to the CYP1B1 mediated increase of growth regulatory genes like cyclin D1 as well as the proliferation, migration and invasion of cancer cells." (PMID 31370872, 2019). "Sp1 and Sp3 regulate EGFR activity through interacting with HDAC1 and HDAC2 in cancer cells." (PMID 31196210, 2019). "Consistent with the crucial roles that Sp1 and E2F1 play in the modulation of miR-203 transcription, overexpression of E2F1 in T24T(shXIAP) cells markedly increased the cancer cell invasion, while knockdown of Sp1 in T24T cells significantly inhibited the cancer cell invasion." (PMID 31811115, 2019). "Next, we demonstrated that the decrease in Daxx levels following HSP27 downregulation in human cancer cells resulted from decreased binding of ETS1 and SP1 to the Daxx promoter (left, middle), whereas HSP25 downregulation in murine cells increased ETS1 binding to the Daxx promoter (right)." (PMID 31615977, 2019). "Importantly, high SP1 levels in various neoplasms are correlated with aggressive behavior, invasive clinical phenotypes, increase recurrence rates, and decreased survival, and both SP1 and EMT markers levels are elevated in cancer cells." (PMID 30976063, 2019).